CD69 (CD69 molecule)
Diseases named in the same sentence as CD69 in open-access papers (continued):
Sharing a sentence is not in itself a finding about the gene and the disease.
asthma (27 papers, 2008 to 2025). "CD69 deficiency has been linked to enhance immune allergic responses that exacerbate asthma and contact dermatitis in experimental models." (PMID 39451246, 2024). "Indeed, the expression of CD69 on eosinophils of other Th2 mediated diseases, such as asthma, is associated with airway inflammation and severity of the disease." (PMID 24348679, 2013). "↑ T lymphocytes (CD3+), Treg (CD4+CD25+FOXP3+), Tc (CD8+), and NK cells (CD3–CD16+CD56+). ↓ activated T cells (CD25+/CD69+). ↑ immune modulation in asthma." (PMID 40352259, 2025). "The increase in CD69 on leukocytes at the inflamed site is observed in the atopic dermatitis and asthma mouse models." (PMID 38540778, 2024). "In the present study, we observed an increase in CD69 expression in lung tissue eosinophils obtained from OVA-induced asthma mice models compared with healthy as well as peripheral blood eosinophils." (PMID 38540778, 2024). "In humans suffering from severe asthma, NK cell activation measured by expression of CD69 and NKG2D correlated strongly with blood eosinophilia." (PMID 36238293, 2022). "By contrast, the immunosuppressive molecule (CD69) was significantly downregulated, which plays key roles in inflammatory conditions of asthma." (PMID 36439114, 2022). "Flow cytometry showed that the mean fluorescence intensity of CD69 on eosinophils was significantly increased by OEA in patients with asthma compared to healthy controls." (PMID 34079051, 2021). "Knockout of CD69 in a murine asthma model showed increased eosinophil recruitment and enhanced Th2 cytokines in lung tissue." (PMID 22333193, 2012). "This upregulation was correlated with disease severity as well as with the number of infiltrated eosinophils in the tissues, suggesting that an increase in CD69 expression in eosinophils is an important marker of the degree of exacerbation in ECRS patients with asthma." (PMID 38540778, 2024). "Indeed, we previously reported that activated tissue eosinophils in nasal polyps obtained from eosinophilic chronic rhinosinusitis (ECRS) patients with asthma highly expressed CD69." (PMID 38540778, 2024). "In addition, it has been shown that CD69+ ILC3 in peripheral blood correlates with BMI in patients with asthma." (PMID 36979473, 2023). "It is reported that MLC9 and MLC12 are new functional ligands for CD69 and may contribute to asthma pathogenesis." (PMID 35784706, 2022). "To identify whether OEA impacts eosinophil activation, we measured the expression levels of CD69, a well-known marker of eosinophil activation, in eosinophils isolated from the blood of patients with asthma and healthy controls." (PMID 34079051, 2021). "The level of CD69 was higher in patients with asthma than in healthy controls." (PMID 34079051, 2021). "Finally, we confirmed that OEA increased CD69 expression (an eosinophil activation marker) on purified eosinophils from patients with asthma compared to those from healthy controls." (PMID 34079051, 2021). "Thus, CD69 knockout mice show an enhanced severity of different models of inflammatory autoimmune diseases, including collagen-induced arthritis, asthma, myocarditis, and contact dermatitis." (PMID 29038617, 2017). "However, in animal models, CD69 deficiency resulted in counterintuitive increases in proinflammatory responses in animal models such as collagen-induced arthritis and Th2-mediated asthma, suggesting that this pathway may function as a negative regulator of inflammation." (PMID 27861506, 2016). "Furthermore, CD69 affects the disease course in murine models of asthma, arthritis, myocarditis, and tumor immunity as demonstrated in CD69-deficient animals." (PMID 25759842, 2015). "Here, we first measured the percentage of CD69 expressed on eosinophils in ovalbumin (OVA)-induced asthma mouse models, following which we investigated whether CD69 crosslinking on eosinophils induces cytokine release and apoptosis and results in the activation of signaling pathways." (PMID 38540778, 2024).
asthma (continued). "CD69 was known as an early activation marker antigen of lymphocytes, had a crucial role in the pathogenesis of arthritis and allergic airway inflammation and could be a possible therapeutic target for arthritis and asthma in human patients." (PMID 35600600, 2022). "Activation markers of eosinophils in the peripheral blood, including CD125, CD69, and CD193, from moderate asthma patients were compared with healthy donors, but there were insufficient eosinophils in the blood of severe asthmatics for analysis." (PMID 38534377, 2024). "In asthma, eosinophils in BAL expressed CD69 and antibody against human CD69 induced Bcl-2-dependent apoptosis." (PMID 18931086, 2008). "CD69 expression of 2.91% ± 0.76% was observed on lung tissue eosinophils obtained from mice with OVA-induced asthma, whereas no expression was detected in the peripheral blood or in the PBS-treated group." (PMID 38540778, 2024). "In different murine disease models including asthma, arthritis, myocarditis, pathogen clearance, the absence of CD69 expression deeply affects the disease course by exacerbating the disease severity in most cases 37-39." (PMID 37064870, 2023). "Hasegawa and Nakayama proved through mouse experiments that the arthritis inflammation and airway inflammation in mice lacking the CD69 gene were significantly reduced, suggesting that this gene might become a new target for the treatment of arthritis and asthma." (PMID 35002537, 2021). "In different murine disease models, including asthma, arthritis, myocarditis, pathogen clearance, tumor immunity, and IBD, absence of CD69 expression deeply affected the disease course by exacerbating the disease severity in most cases." (PMID 25759842, 2015).
autoimmune disease (27 papers, 2008 to 2025). A disorder resulting from loss of function or tissue destruction of an organ or multiple organs, arising from humoral or cellular immune responses of the individual to their own tissue constituents. "Increased expression of CD52 and CD69 suggests a compensatory mechanism to overcome age-related decline in immune function and an excessive immune response associated with autoimmune diseases." (PMID 41226506, 2025). "For example, while some studies have implicated the loss of CD69 and autoimmune diseases, others show that CD69 stimulates immune response." (PMID 36045683, 2022). "Several studies associate the blocking or lower expression of CD69 in T cells with an exacerbation of autoimmune diseases and a higher induction of pro-inflammatory Th17 cells in mice." (PMID 32431704, 2020). "By the study of CD69-deficient mice, CD69 has been defined as a regulator of the immune response in different murine models of tumor, infection, autoimmune disease and other inflammatory models." (PMID 31466317, 2019). "In women with long-term type 1 diabetes and an associated autoimmune disease, there was an increase in CD69 expression and a decrease in the survival B-cell lymphoma 2 (BCL-2) (p < 0.05) and CD127 (IL-7R) (p < 0.01) marker expression compared with women without a concomitant autoimmune disorder." (PMID 34350463, 2021). "In line with this assumption, we showed that also in T cells from patients with autoimmune diseases, PL led to reduced expression of the T cell activation markers CD69 and CD25 and diminished production of IFNγ and IL-2." (PMID 32595640, 2020). "In vivo studies in CD69 KO mouse models have demonstrated an important role of CD69 in the pathogenesis of different inflammatory and autoimmune diseases, and a critical function in the anti-infectious, anti-tumoral and airway inflammatory responses." (PMID 33193627, 2020). "CD69+ Tregs have the potential to develop new therapeutic approach for autoimmune diseases like IBD." (PMID 30185773, 2018). "The Q70W heightened induction of CD69 and CD25 could potentially lead to excessive T-cell activation, disrupting the immune balance and increasing the risk of autoimmune diseases and chronic inflammation." (PMID 40711587, 2025). "Upregulated CD69-expressing immune cells in blood have been reported in autoimmune disorders, such as psoriasis and Graves’ disease, although CD69-expressing cells have been suggested to either promote or reduce disease progression in models of systemic lupus erythematosus." (PMID 41373029, 2025). "Specifically, both C15:0 and metformin had significant, dose-dependent effects on lowering: HLA-DR in the 3C system relevant to cardiovascular disease and chronic inflammation; and CD38, CD69, and T cell proliferation in the SAg cell system relevant to autoimmune disease and chronic inflammation." (PMID 37960259, 2023). "Furthermore, in T cells from patients with different autoimmune diseases PL inhibits the expression of the T cell activation markers CD69 and CD25 as well as production of IFNγ and IL-2." (PMID 32595640, 2020). "A lower expression of CD69 in T cells could be related to a defective control of inflammation and a worse evolution of autoimmune diseases." (PMID 32431704, 2020). "Paradoxically, CD69−/− mice exhibit enhanced tumor immunity and enhanced susceptibility to autoimmune disease raising the possibility that the molecule is a negative regulator of T cell activation." (PMID 26433463, 2015). "By increasing HSF1 protein levels, proteasome inhibitors (PSIs) such as MG132 and the anti-tumor drug bortezomib could promote the generation of CD69+ Tregs, thus offering a practical approach to generate potent iTregs for the treatment of colitis and probably other autoimmune diseases." (PMID 37064870, 2023).
autoimmune disease (continued). "It has potent immunosuppressive properties by producing sufficient amounts of IL-10 and TGF-β1 18, indicating that the generation of CD69+ Tregs may be a new approach to harvest Tregs with sufficient potency for the treatment of various autoimmune diseases involving Treg insufficiency." (PMID 37064870, 2023). "Premature ovarian insufficiency is an autoimmune disease, the numbers of effector Treg cells decreased, and CD4+ CD69+ activated T cells in peripheral blood increased." (PMID 38125684, 2023). "TRM cells are tissue-resident cells characterized by expression of high CD69 and/or CD103, which play an important role in the maintenance of respiratory homeostasis and autoimmune diseases." (PMID 33855090, 2021). "Of 223 hypomethylated regions identified, several were in promoters of autoimmune disease GWAS loci (ARID5B, CD69, HDAC9, IL7R, TNIP1 and TRAF1)." (PMID 32231389, 2020). "MAIT cell (total, CD8+, DN) frequencies and CD69 expression contributed to segregation between women with long-term diabetes with or without another autoimmune disease." (PMID 34350463, 2021). "The identification of CD69+Tregs may aid in the design of new therapies for the control of IBD and probably other autoimmune diseases." (PMID 30185773, 2018). "Several correlations between CD27 and other MAIT cell variables, such as a positive correlation with MAIT cell frequency and negative correlations with CD69 and PD1 expression by MAIT cells, were only observed in the women with long-term type 1 diabetes and another autoimmune disease." (PMID 34350463, 2021).
systemic lupus erythematosus (26 papers, 2008 to 2025). An autoimmune multi-organ disease typically associated with vasculopathy and autoantibody production. "Others have shown increased numbers of CD4+CD69+ T cells with altered expression of interleukins and suggested a correlation with loss of self-tolerance in lupus mice." (PMID 34733276, 2021). "First, CD69 is involved in systemic lupus erythematosus (SLE), rheumatoid arthritis, atopic dermatitis, and systemic sclerosis, as well as animal models of arthritis, myocarditis, and inflammatory bowel disease." (PMID 38750122, 2024). "It has been proved that CD69 and HLA-DR evoke vital function in many resist diseases, including rheumatoid arthritis and systemic lupus erythematosus." (PMID 35600045, 2022). "Of clinical significance, a human study in lupus patients also found that CD69+ T cells are increased and defective in function." (PMID 34733276, 2021). "CD4+ T cells from anti-dsDNA IgG-producing lupus-prone TC mice showed an increased expression of the early activation marker CD69, as well as an accumulation of effector memory T (TEM) and TFH cells as compared to B6 controls." (PMID 30348969, 2018). "Others have correlated an increase in CD69 expression on MAIT cells with systemic lupus erythematosus and ulcerative colitis." (PMID 29312341, 2017). "The CD8+ T cells from the brains of lupus-prone mice exhibited substantial CD69 and PD-1 upregulation and CD122 downregulation relative to peripheral CD8+ T cells from the same mice, indicative of a Trm cell phenotype." (PMID 28098193, 2017). "CD69 expression on MAIT cells in patients with lupus positively correlated with plasma concentrations of IL-6, IL-18, and IFN-α." (PMID 28288675, 2017). "In line with this are reports of a diminished number of activated CD69+ or CD154+ T cells after successful B cell depletion therapy in humans with systemic lupus erythematosus." (PMID 27558631, 2016). "Macrophages contain 1α-hydroxylase and are therefore capable of autocrine or paracrine activation of vitamin D. In the context of local dermal inflammation, CD69 overexpression has been reported in systemic lupus erythematosus (SLE), Graves’ disease (GD), and Hashimoto’s thyroiditis (HT)." (PMID 40429939, 2025). "Previous studies have indicated that rituximab may affect T-cell responses in systemic lupus erythematosus patients through downregulation of activation and co-stimulatory molecules (for example, CD69, CD154)." (PMID 19715572, 2009). "In this study, we analyzed the levels and function of CD4+CD69+ Treg cells in patients with systemic lupus erythematosus (SLE)." (PMID 29038617, 2017). "SNORA12 expression is downregulated in T cells from systemic lupus erythematosus (SLE) patients and regulates the expression of CD69, HIST1H4K by promoting interferon production of T cells." (PMID 37006268, 2023). "This study found a correlation between CD38 with FoxP3 expression and immunosuppressive molecules (CD69, IL-10, CTLA-4, and PD-1) in T-cells from lupus-prone mice (B6.MRL-Faslpr/J)." (PMID 34769406, 2021). "RN-486 suppresses IgG anti-dsDNA secretion, blocks CD69 expression in response to BCR crosslinking, and completely inhibits progression of glomerular nephritis in systemic lupus erythematosus (SLE) prone NZB/W mouse models." (PMID 23958373, 2013). "Freshly isolated SMCs from pristane-induced lupus mice were activated with ConA (2.5 μg/ml) with or without resveratrol and the levels of CD69 and CD71 were then measured, which are markers of CD4+ T lymphocyte activation." (PMID 25501752, 2014). "Lupus patients had significantly increased proportions of activated B cells, as demonstrated by the increased percentage of CD20+ cells with elevated levels of CD69 and increased proportion of CD86+ cells in the CD27+ B-cell compartment." (PMID 18783591, 2008).
systemic lupus erythematosus (continued). "Actually, lupus NK cells present a strong basal activation level and seem to be exhausted, as shown by both the high CD69 expression in medium and the moderate response (not reaching significance) to the TLR9 agonist, respectively, suggesting that NK cells have been pre-activated in vivo." (PMID 34012432, 2021). "Despite previous reports in the literature indicating increased autoantibody production in the relatives of lupus patients, the proportions of activated B cells, as determined by expression levels of CD69, CD80, and CD86, were not increased in the family members of our lupus patients." (PMID 18783591, 2008).
colitis (24 papers, 2011 to 2025). Inflammation of the colon. "TIGIT deficiency protected micefrom induction of experimental colitis by reducing IL-17Aproducing CD69+CD103-CD4+ TRM cells." (PMID 40529369, 2025). "TIGIT deficiency protects mice from DSS-induced colitis by reducing IL-17A–producing CD69+CD103− CD4+ TRM cells." (PMID 35844584, 2022). "The same was observed in a chemically induced colitis model when dextran sodium sulfate (DSS) was administrated to CD69-deficient mice." (PMID 25759842, 2015). "In several different models of experimental colitis, the deficiency of CD69 led to a very serious clinical picture of the disease." (PMID 25759842, 2015). "The transfer of CD69-deficient CD45RBhigh CD4 T cells into RAG KO hosts induced accelerated colitis." (PMID 23785429, 2013). "Administration of 2% DSS in the drinking water induced severe colitis in CD69-deficient mice as observed by the accelerated body weight loss compared to the DSS treated B6 animals and non-treated control group." (PMID 23776480, 2013). "Both acute and chronic colitis were attenuated in the CD69 KO mice, as reflected by the lower lethality, weight loss, clinical signs, and improved histological findings." (PMID 23785429, 2013). "CD69-deficient animals treated with neutralizing Abs showed the signs of mild colitis, with normal number of goblet cells, slightly elongated colonic crypts and few infiltrating inflammatory cells." (PMID 23776480, 2013). "The transfer of CD69-deficient CD45RBhigh CD4 T cells into RAG-deficient hosts induced accelerated colitis." (PMID 23785429, 2013). "For example, the adoptive transfer of CD69-deficient CD4+ T cells into RAG-/- mice (deficient in lymphocytes) induced severe colitis due to the increased secretion of proinflammatory cytokines (IFN-γ, TNF-α, IL-21) and decreased levels of anti-inflammatory cytokines (TGF-β1)." (PMID 39451246, 2024). "Here, our data uncover a pathogenic role of CD69+CD103− CD4+ TRM cells in DSS-induced colitis." (PMID 35844584, 2022). "In CD69-deficient (CD69 KO) mice, both acute and chronic colitis were attenuated." (PMID 23785429, 2013). "In contrast, HSF1 protein stabilized by inhibiting its proteasomal degradation promoted CD69+ Treg differentiation and alleviated colitis in mice." (PMID 37064870, 2023). "Similar to the results of the in vitro experiments, the sorted CD69+ iTregs from Control-iTregs or PSI-iTregs exerted similar effects on the colitis treatment." (PMID 37064870, 2023). "Nevertheless, CD69 seems to be critical for the immunosuppressive potency of Tregs to inhibit the development of colitis." (PMID 37064870, 2023). "To further confirm the relevance of CD69+ Tregs in colitis, we generated iTregs under Treg polarization conditions in vitro." (PMID 37064870, 2023). "Genetic and chemical inhibition of HSF1 impaired CD69+ Treg differentiation and promoted the pathogenesis of colitis in mice." (PMID 37064870, 2023). "In summary, PSIs promotes the in vitro differentiation of CD69+ iTregs to enhance the immune suppressive function of iTreg, thus representing a novel approach to obtain sufficient iTregs for colitis therapy." (PMID 37064870, 2023). "In contrast, we observed a decreased percentage of CD8+CD69+CD103+ TRM cells in LPMC from DSS-induced colitis." (PMID 35844584, 2022). "TIGIT deficiency impairs IL-17A production in CD69+CD103− CD4+ TRM cells specifically, resulting in lower disease activity index and reduced pathological injury in mice with DSS-induced colitis." (PMID 35844584, 2022). "TIGIT deficiency led to decreased numbers of CD69+CD103− and CD69+CD103+ CD4+ TRM cells in the colon during DSS-induced colitis." (PMID 35844584, 2022). "Here, we showed that TIGIT was required for IL-17A production by CD69+CD103− CD4+ TRM cells during DSS-induced colitis." (PMID 35844584, 2022). "CD69+CD103− CD4+ TRM cells are the major source of IL-17A production in the gut of mice with DSS-induced colitis." (PMID 35844584, 2022).